CXCL8 (C-X-C motif chemokine ligand 8)
Diseases named in the same sentence as CXCL8 in open-access papers (continued):
Sharing a sentence is not in itself a finding about the gene and the disease.
tumor (continued). "In addition to enhancing local inflammatory responses in the tumor by recruiting immune cells, CXCL8 may also promote tumor development by promoting tumor cell growth, angiogenesis and metastasis." (PMID 41376630, 2025). "Furthermore, the upregulation of CXCL8 (IL-8) and CXCL2 observed in our 3D spheroid cultures may contribute to the recruitment and accumulation of tumor-associated neutrophils within TME." (PMID 39193365, 2024). "Through single-cell transcriptomic sequencing, we discovered that the monocyte_C02 subpopulation is more prevalent in right-sided colorectal cancer, and its highly expressed genes, such as CXCL8, TNFAIP6, CXCL3, and SPP1, may be implicated in tumor growth promotion." (PMID 38711918, 2024). "Thus, LAPTM4B-secreted CXCL8 drove MDSCs migration into tumor tissues." (PMID 38388484, 2024). "Additionally, CXCL6, together with other immune modulators such as CXCL8 and IL-8, contributes to the formation of an immunosuppressive microenvironment that facilitates tumor escape from immune surveillance, thereby promoting cancer progression and resistance to therapy." (PMID 39741907, 2024). "Furthermore, each classifier identified in our study can serve as a potential marker for CRC, and the effects of these classifiers may be modulated by critical genes such as PSMC2 and CXCL8, which are associated with CRC of different tumor stages." (PMID 38243058, 2024). "Additionally, both tumor and non-tumor samples exhibited elevated CXCL8 expression levels, and these were associated with an unfavorable prognosis." (PMID 38673838, 2024). "In a mouse fibrosarcoma model, CXCL8 induced neutrophil infiltration into the tumor, and the magnitude of neutrophil infiltration correlated with genotoxic ROS (reactive oxygen species) and RNS (reactive nitrogen species), as well as the mutational burden of tumor cells." (PMID 38786066, 2024). "Therefore, LAPTM4B drove MDSCs migration toward tumor tissue primarily via CXCL8." (PMID 38388484, 2024). "Similarly, several studies have indicated that CXCL8 is related to tumor migration and invasion." (PMID 39188951, 2024). "A positive association between circulating IL-8 levels and tumor mRNA expression of CXCL8, and an inverse correlation with tumor IFNγ and T cell signatures were also reported, demonstrating that circulating levels of IL-8 are reflective of changes in the tumor microenvironment." (PMID 38493133, 2024). "Interestingly, GW showed a favourable effect in inhibiting angiogenesis of OE-MLKL tumours, which might be attributed to its necroptosis-inhibitory role and thereby mitigated the activation of CXCL8, a cytokine known to promote angiogenesis." (PMID 39025845, 2024). "The IL-8/CXCL8 autocrine signaling in tumor cells could promote the formation of NETs." (PMID 38520006, 2024). "Therefore, CXCL8 can recruit suppressor cells to the tumor microenvironment by recognizing CXCL1." (PMID 36647133, 2023). "Furthermore, higher expressions of CXCL1, CXCL3, and CXCL8 in the high UVRAG expression group also indicated that UVRAG expression had a relationship with promoting tumor progression, angiogenesis, and immune suppression by recruiting tumor-associated macrophages (TMAs)." (PMID 37173968, 2023). "Furthermore, we can conclude that serum CXCL8 might be a better biochemical marker candidate in the diagnosis of CRC than the classical tumor marker used in routine clinical practice." (PMID 37509572, 2023). "Notably, CXCL1 and CXCL8, which are the key functional genes in the hallmark pathway of EMT, are essential for the activation and trafficking of inflammatory mediators as well as tumor progression and metastasis." (PMID 37940972, 2023). "In addition, CXCL8 acts in an autocrine manner, promoting tumor cell growth and survival." (PMID 37760903, 2023). "Additionally, PTC-derived TAM promotes tumor invasion and metastasis by producing CXCL8." (PMID 38250858, 2023).
tumor (continued). "Peripheral serum CXCL8 levels were found to have positive correlation with tumour necrosis percentage, and such tendency was also observed between the mesenteric vein serum CXCL8 and tumour necrosis percentage, suggesting that CXCL8 may transmit the protumor signals related to tumour necrosis." (PMID 37031328, 2023). "Therefore, blocking the CXCL8-CXCR1/2 axis by using small molecules or antibodies were testes, such as SB225002 (CXCL8 inhibitor binding to CXCR2) to inhibit tumor progression in HER2+ breast cancer, and danirixin (GSK1325756) to suppress cancer migration, invasion, and metastasis." (PMID 36835413, 2023). "Therefore, the expression level of CXCL8 can be used as an indicator of tumor prognosis." (PMID 36647133, 2023). "CXCL8 may have a role in the systemic effects of tumour necrosis." (PMID 37031328, 2023). "In addition, the PAS+CD34− GC tumor cells expressed high levels of CXCL8 in EBVaGC." (PMID 35321317, 2022). "Furthermore, several investigations have indicated that CXCL8 plays a vital role in the process of the Ras signaling pathway initiating angiogenesis, which can promote tumor angiogenesis by promoting the expression of VEGR or directly acting on vascular endothelial cells." (PMID 35845924, 2022). "Moreover, a study described CXCL8 as a link between tumor metabolism and angiogenesis." (PMID 35626056, 2022). "Thus, it could be confirmed that CXCL8 widely affected immune infiltration in the tumor microenvironment." (PMID 36532065, 2022). "In particular, the chemokine CXCL-8 may induce immune infiltration in tumours and account for the response to ICIs also in the absence of pre-existing immune infiltration and PD-L1 expression on tumour cells." (PMID 35207291, 2022). "Therefore, GI may affect the expression of CXCL8, leading to the change of M2 cell infiltration and finally influencing the tumor immune microenvironment." (PMID 36118853, 2022). "Thus, promoting CXCL8 secretion by cancer cells might not only favor the recruitment of NK cells but also promote tumor infiltration by immunosuppressive cells that may offset therapeutic efficacy." (PMID 36319998, 2022). "Therefore, our study suggests that serum CXCL-8 may serve as an improved biomarker for CRC diagnosis compared to the traditional tumor markers CEA and CA19-9." (PMID 36567905, 2022). "Therefore, CXCL8 inhibitors may drive an anti-tumor response and could be a novel approach in treating GC patients." (PMID 36185234, 2022). "Besides, cluster 2 and 3 overexpressed genes CXCR4 and CXCL8 for tumor microenvironment." (PMID 35986270, 2022). "In addition, tumor-derived CXCL8 can traffic M2 macrophages and mediate local immunosuppression." (PMID 36118853, 2022). "Therefore, we can speculate that serum CXCL-8 might be a better candidate as a tumor biochemical marker for the diagnosis of CRC than the routine clinical practice markers CEA and CA19-9." (PMID 36567905, 2022). "Therefore, in our most recent studies we investigated whether serum CXCL-8 and its specific receptor (CXCR-2) may be used as potential biochemical tumor markers for CRC using the enzyme-linked immunosorbent assays (ELISA) method." (PMID 34071492, 2021). "We further investigated whether CXCL8 could regulate tumor progression in vivo." (PMID 34025668, 2021). "Clearly, the activation of secretory autophagy in tumor and stromal cells results in the release in the extracellular space of a number of factors, including inflammatory cytokines and chemokines (e.g., interleukin 1β, CXCL8, LIF), thus impacting on the tumor microenvironment." (PMID 34944948, 2021). "In addition, CXCL8 is closely related to the formation of tumor growth environment." (PMID 34869316, 2021). "Thus, pulmonary complications may be related to tumor progression by promoting inflammatory cytokines, such as CXCL8, which negatively affects CSS and DFS." (PMID 34640631, 2021).
tumor (continued). "Moreover, CXCL8 was revealed to play a significant role by promoting tumor formation, progression, and invasion via activating phosphoinositide 3-kinase (PI3K) signaling, which subsequently phosphorylates protein kinase B (PKB) also known as (AKT) and MAPK in breast cancer and CRC." (PMID 34440739, 2021). "Additionally, in the complex tumor micro environment, CXCL8 as a chemokine may act as an antitumor factor through other subtypes of cells." (PMID 34025668, 2021). "CXCL8 signaling could not only promote angiogenesis, and proliferation and survival of endothelial cells, but also increase progression of cancer cells, infiltrating neutrophils with both pro- and antitumor properties at the tumor site." (PMID 33364190, 2020). "Administration of a dual CXCR1/2-targeted antagonistic peptide alone inhibited the growth of PTEN-deficient but not PTEN-expressing DU145 and PC3 xenograft tumours, consistent with our prior and current demonstration of CXCL8 functioning as a key survival factor in this genetic context." (PMID 32743555, 2020). "Furthermore, some authors have indicated that CXCL-8 overexpression is correlated with the presence of distant metastases and general tumor progression, which may indicate the potential usefulness of this protein as a marker of progression of this disease." (PMID 32192002, 2020). "Furthermore, through analysis of gene expression levels in tumor and normal samples and survival analysis, CXCL8, KIF18A, and E2F1 showed high expression and poor prognosis, which indicated that they may play a role in promoting ESCA progression." (PMID 32851080, 2020). "Therefore, the aim of the present study is to investigate whether chemokine CXCL-8 may be used as a potential biochemical tumor marker for CRC." (PMID 32192002, 2020). "Furthermore, the positive predictive value (PPV) for CXCL-8 levels was higher than that for SCC-Ag, but lower than that for CRP and CEA, while the diagnostic accuracy of CXCL-8 was marginally lower than that of CRP, but higher than that of the classical tumor markers." (PMID 30820705, 2019). "However, following stimulation by TNFα, the equilibrium between the two cell types was changed: not only the tumor cells but also MSCs - although at lower levels - contributed to the elevation in CXCL8 expression by the cytokine-stimulated co-cultures (Figure 3A2)." (PMID 31105691, 2019). "Overall, our studies identify novel tumor-stroma-inflammation networks that may promote TNBC aggressiveness by increasing the pro-malignancy potential of the TME and of the tumor cells themselves, and reveal key roles for CXCL8 in mediating these metastasis-promoting activities." (PMID 31031757, 2019). "Therefore, the aim of the current study was to measure serum concentrations of chemokine CXCL-8 in OC patients and establish whether this protein might be considered a potential candidate for a tumor marker in the diagnosis and progression in OC patients." (PMID 30820705, 2019). "Therefore, in our present study, we evaluated whether serum CXCL-8 levels might be used as a potential tumor marker for OC." (PMID 30820705, 2019). "Failure to completely abolish CXCL8 secretion in the tumor microenvironment appears in line with the notion that CXCL8 secretion results from multiple intracellular signals and/or pathways, which appear to be different when normal or tumor cells are taken into account." (PMID 29977225, 2018). "Mechanistically, high PIM levels increase the recruitment of tumor/inflammation associated macrophages, MDSCs, mast cells, and neutrophils to the target tissue, by increasing IL-6 locally as well as other cytokines (such as OSM) and probably other chemokines (such as CCL2 and CXCL8)." (PMID 28938604, 2017).
tumor (continued). "In this regard, high PIM levels increase the recruitment of tumor/inflammation associated macrophages, MDSCs, mast cells, and neutrophils to the target tissue, which can increase cytokines, such as IL-6, IL-1 and TNFa, and chemokines, such as CCL2 and CXCL8, locally." (PMID 27901106, 2016). "Similarly, serum CXCL8 protein levels have been correlated with tumor burden in RCC patients." (PMID 26859141, 2016). "Importantly, both stromal and tumor cells can produce CXCL8." (PMID 26648665, 2015). "Interestingly, CXCL8, which is abundantly produced by tumor cells, is released in the surrounding environment, representing a potent chemoattractant for neutrophils within the tumor mass." (PMID 25072019, 2014). "CXCL8 may also contribute to tumor growth, while CCL5 may induce anti-tumor responses." (PMID 25201625, 2014). "Therefore, agents that target these transcription factors may, indirectly, also target tumor-derived CXCL8." (PMID 24276377, 2013). "Thus, the CXCL8 immunoreactivity detected within the tumour infiltrate may correlate with increased activity of the immune cells." (PMID 21285972, 2011). "Additionally, CXCL8 expression was characterized throughout the immune infiltrate of the tumours." (PMID 21285972, 2011). "Tumours formed from FPS cells expressed significantly higher CXCL8 mRNA as compared to WT tumours indicating that there was sufficient endogenous PGF2α in nude mice to induce CXCL8 expression in vivo via the FP receptor similar to our observations in these cell lines vitro (data not shown)." (PMID 19819266, 2009). "Moreover, CXCL8 expression revealed a close correlation with tumor grading." (PMID 18578857, 2008). "Interleukin‐8 (IL‐8), also known as CXCL8, is a proinflammatory CXC chemokine (or α‐chemokines) secreted by monocytes, tumor cells, endothelial cells, and neutrophils." (PMID 40968783, 2026). "Several proteins, including S100A7, IL1RN, and CXCL8, were identified as potential biomarkers for HPV-positive tumours." (PMID 41487403, 2026). "Our results suggest that N4BP1 controls multiple targets, such as CCL2, GM-CSF, CXCL8, and S100A2, to regulate multiple tumor malignant behaviors." (PMID 41513619, 2026). "Kaempferol, a major flavonol widely found in various fruits and vegetables, downregulated the expression of key inflammatory mediators (IL-1β, CXCL8, and MMP9), then reducing neutrophil infiltration and activation while inhibiting tumor growth in CRC." (PMID 41601690, 2026). "Angiogenesis is key to CRC progression, and CXCL8 promotes CRC angiogenesis through the CXCR2 receptor, providing survival resources for the tumor and creating conditions for metastasis." (PMID 40626716, 2025). "Abnormal tumor vessels further exacerbate hypoxia, which in turn increases the secretion of chemotactic cytokines - including CCL2, CCL22, CCL28, CXCL8, and CXCL12 - that recruit immunosuppressive MDSCs, M2-like TAMs, and Tregs into the tumor." (PMID 41019982, 2025). "By inhibiting the binding of CXCL8 and CXCR1/2, the aggregation of immunosuppressive cells (e.g., neutrophils, TAMs, etc.)in the TME can be reduced, thereby promoting the anti-tumor activity of effector T cells." (PMID 41376630, 2025). "Nevertheless, interleukin-8, also known as CXCL8, binds to the receptors CXCR1 and CXCR2 has been shown to mediate tumour progression, epithelial-mesenchymal transition, invasion, and angiogenesis." (PMID 40852716, 2025). "The cluster 6 monocytes were defined by high expression of multiple pro-tumor genes (IL1B, SERPINB2, CCL2, CXCL1, CXCL5, CXCL8, CCL3, CCL20)." (PMID 40176808, 2025). "Our study demonstrates significant upregulation of CXCL8 in ESCA cell lines, highlighting its potential as a key driver of tumor progression in this malignancy." (PMID 40087784, 2025). "Attraction of mobilized neutrophils to the tumor site is realized via chemokines CXCL1, CXCL2, CXCL5, CXCL6, and CXCL8 (IL-8) through CXCR1/2 and CXCL12 (SDF-1) and its receptor CXCR4." (PMID 40050933, 2025).
tumor (continued). "CXCL8 recruitment and activation of neutrophils by binding to CXCR1 and CXCR2 has been shown to enhance tumor growth and proliferation through secretion of a variety of cytokines and angiogenic factor release." (PMID 41376630, 2025). "Recent studies have demonstrated a relationship between CXCL8 and components of the TME, revealing new crosstalk mechanisms that can promote tumor progression and potentially establish a positive feedback loop." (PMID 40006729, 2025). "For instance, in NSCLCs, the tumour cells over expressing ACKR1 internalises and immobilise the bound ligands CXCL5 and CXCL8 thereby restricting the downstream signalling for angiogenesis and metastasis." (PMID 40852716, 2025). "Circulating monocytes are instead retained at the CD1a+ stage by GM-CSF, CXCL8, and CCL2 gradients in the primary tumor, turning the pCRC into a functional “monocyte reservoir”." (PMID 41410751, 2025). "Key chemokines involved in this process include CXCL1, CXCL2, and CXCL8 (IL-8), which bind to the CXCR1 and CXCR2 receptors on neutrophils, guiding them to the tumor site." (PMID 41180630, 2025). "Tumor cells secrete chemokines like CCL5, CCL7, and CXCL8, which recruit Treg cells and MDSCs into TME." (PMID 40672434, 2025). "Further studies found that inhibition of CXCL8 and its receptor chemokines CXCR1 and CXCR2 promote G1 cell cycle arrest and apoptosis, suggesting that CXCR1 and CXCR2 inhibit tumor progression in prostate cancer by influencing cell proliferation." (PMID 41347146, 2025). "Further analysis revealed a positive correlation between CXCL8 expression in pMQs and its receptors, CXCR1 and CXCR2, in matched tumor cells." (PMID 39937005, 2025). "CXCL8 correlated strongly with neutrophils and macrophages, suggesting its role in modulating immune responses in the ESCA tumor microenvironment." (PMID 40087784, 2025). "In CRC, stimulated by TNF-α, Granulocyte-macrophage colony-stimulating factor (GM-CSF), Platelet-activating factor (PAF), and CXCL8, neutrophils release CXCL8, CXCL1, and VEGF, inducing tumor angiogenesis." (PMID 41346579, 2025). "CCL4, CXCL8, and MIF have received considerable attention for their roles in tumor proliferation, differentiation, angiogenesis, and tumor progression." (PMID 40092701, 2025). "Within TME, inflammatory cytokines, in particular IL-6 and IL-8 (CXCL8), contribute to different tumor-promoting mechanisms, such as cancer cell plasticity, angiogenesis, and immunosuppression." (PMID 41306965, 2025). "The activation of S100A10 in lung fibroblasts via tumour‐derived exosomes can increase the expression of chemokines CXCL1 and CXCL8, contributing to MDSCs recruitment and lung PMN formation." (PMID 40032646, 2025). "Tumor cells and stromal cells secrete a variety of chemokines and cytokines, including cysteine X cysteine ligands such as CXCL1, CXCL2, CXCL5, and CXCL8 (IL-8), that attract neutrophils to the tumor site." (PMID 40227814, 2025). "In our investigation, we examined the expression of genes connected to stemness in the different tumor cell subtypes and determined that the expression levels of ATF3, CXCL2, RRAD, AREG, and CXCL8 were significantly higher in the C0 subtype." (PMID 40936936, 2025). "Macrophages and neutrophils in the tumor microenvironment shape a cytokine milieu (IL-6, IL-1β, TNF, CXCL8) that supports tumor growth and metastasis and counteracts antitumor immunity." (PMID 41440484, 2025). "IL-6, TNF-α, and CXCL8 are three key pro-inflammatory cytokines extensively involved in remodeling the TME, thereby promoting tumor cell proliferation, metastasis, and immune evasion." (PMID 41376630, 2025). "In clinical diagnostics, specific chemokines (e.g., CXCL8 and CCL2) serve as valuable biomarkers, with their expression levels demonstrating significant correlations with tumor stage and prognosis." (PMID 41445742, 2025).